POLDIP2 (DNA polymerase delta interacting protein 2)
Diseases named in the same sentence as POLDIP2 in open-access papers (continued):
Sharing a sentence is not in itself a finding about the gene and the disease.
Stroke (2 papers, 2018 to 2020). Sudden impairment of blood flow to a part of the brain due to occlusion or rupture of an artery to the brain. "It has been demonstrated that Poldip2 is responsible for the upregulation of MMPs activity in hindlimb ischemia‐induced mice and stroke animal model, but very little is known about the molecular mechanism of Poldip2 in regulating MMPs." (PMID 32790044, 2020). "Compared to Poldip2+/+ mice, Poldip2+/− animals exhibited decreased Evans blue dye extravasation and improved survival 24 h following stroke." (PMID 29452577, 2018). "Next, we analyzed the impact of Poldip2 depletion on motor performance after stroke by employing the RotaRod test." (PMID 29452577, 2018). "Our study demonstrated that the expression and activity of both MMP2 and MMP9 in BM animal model are upregulated by exogenous Poldip2 and downregulated by Poldip2 knockdown, corroborating the results of previous studies in hindlimb ischemia‐induced mice and stroke animal model." (PMID 32790044, 2020).
acute lung injury (1 paper, 2022). A condition of lung damage that is characterized by bilateral pulmonary infiltrates (pulmonary edema) rich in neutrophils, and in the absence of clinical heart failure. "Polymerase δ-interacting protein 2 (Poldip2) has been reported to mediate acute lung injury (ALI); however, the underlying mechanism is not fully explored." (PMID 36120334, 2022).
bacterial meningitis (1 paper, 2020). Inflammation of the membranes surrounding the brain and spinal cord due to a bacterial infection. "The mechanism of AQP4 polarity loss being induced by Poldip2 in mouse bacterial meningitis model is summarized in graphical abstract." (PMID 32790044, 2020). "Schematic illustration of AQP4 polarity loss being induced by Poldip2 in mouse bacterial meningitis model." (PMID 32790044, 2020). "This study aimed to investigate whether Poldip2‐mediated BBB disruption and cerebral edema formation in mouse bacterial meningitis (BM) model occur via induction of AQP4 polarity loss." (PMID 32790044, 2020).
endothelial dysfunction (1 paper, 2021). In vascular diseases, endothelial dysfunction is a systemic pathological state of the endothelium (the inner lining of blood vessels) and can be broadly defined as an imbalance between vasodilating and vasoconstricting substances produced by (or acting on) the endothelium. "In conclusion, Poldip2 is an important mediator of endothelial dysfunction and leukocyte recruitment." (PMID 33692398, 2021).
lung carcinoma (1 paper, 2016). "For each unit increase in the relative expression of POLDIP2 gene, the odds of having lung cancer decreased by 72% and 99% for younger and older men, respectively." (PMID 27418131, 2016). "Each unit increase in the relative expression of the EIF2S3, POLDIP2, and RNF4 genes showed protective effects, with odds of having lung cancer decreased by 78%, 84%, and 78%, respectively." (PMID 27418131, 2016).
viral infection (1 paper, 2026). "Poldip2 also modulated the inflammatory response to viral infection in a heterogeneous manner, reflecting its diverse regulatory roles." (PMID 42054341, 2026).
tumor (6 papers, 2010 to 2022). "Furthermore, POLDIP2 has been implicated in tumor growth and invasiveness in non-small cell lung cancer." (PMID 31801939, 2019). "As shown in the mechanism study, POLDIP2 knockdown can significantly impair the expression of cell proliferation, cyclin D1, epithelial mesenchymal transition (EMT) markers, cdh2, and slug and twist, thereby indicating that POLDIP2 participates in regulating tumor growth and invasiveness." (PMID 36425112, 2022).
cancer (3 papers, 2010 to 2022). A tumor composed of atypical neoplastic, often pleomorphic cells that invade other tissues. "So far, research on POLDIP2 is the most extensive and comprehensive, focusing mainly on cardiovascular disease, neurological disease, renal disease, and cancers." (PMID 36425112, 2022). "In fact, many experiments in earlier publications describing Poldip2 function and localization were performed in immortal or cancer cell lines such as HEK293, HeLa, and C2C12." (PMID 24797518, 2014). "The POLDIP2 gene was found to function as an oncogene in NSCLC, suggesting that it may have the ability to cause cancer via stimulating cell proliferation or epithelial mesenchymal transition (EMT)." (PMID 36425112, 2022). "Our analysis of the literature on the members of the TNFAIP1/POLDIP2 SFGM confirmed a previous suggestion regarding its functional integrity and its possible importance in cancers." (PMID 20158880, 2010).
infection (1 paper, 2026). The state of being infected such as from the introduction of a foreign agent such as serum, vaccine, antigenic substance or organism. "Our data show that Poldip2 expression was elevated in human lung vascular endothelium after infection." (PMID 42054341, 2026). "However, seven days after infection, Poldip2 knockdown reduced viral load, decreased infiltration of myeloperoxidase (MPO)-positive neutrophils into inflamed lungs, and reduced tissue damage." (PMID 42054341, 2026).
inflammation (1 paper, 2022). Aberrant reaction of the microcirculation characterized by movement of fluid and leukocytes from the blood into extravascular tissues. "Collectively, our results suggested that Poldip2 knockdown attenuated LPS-induced lung inflammation via inhibits NF-κB signaling pathway." (PMID 36120334, 2022).
POLDIP2 also shares sentences with these, for which no sentence is quoted: aortic aneurysm (1 paper); cardiovascular disease (1); cataract (1); COVID-19 (1); diabetes (1); diabetic retinopathy (1); Hyperglycemia (1); leukemia (1); lung disease (1); macular degeneration (1); neurological disease (1); renal disease (1); renal fibrosis (1); thyroid disease (1).